CD47 (CD47 molecule)
Diseases named in the same sentence as CD47 in open-access papers (continued):
Sharing a sentence is not in itself a finding about the gene and the disease.
lung cancer (continued). "Furthermore, by performing an immunofluorescence assay, we found that RAGA partially colocalized with CD47 in both HBE normal cells and A549 lung cancer cells." (PMID 36823443, 2023). "Overall, HIIT combined with targeting IL-10, CD47 and CD24 could be a novel strategy for the treatment of lung cancer." (PMID 36186906, 2022). "In lung cancer, the CCL25/CCR9 axis promotes cancer progression, but intratumoral delivery of CCL25 attracts CCR9+ CD8+ T cells to infiltrate the tumor and enhances CD47-targeted immunotherapy in a murine TNBC model." (PMID 34771505, 2021). "Targeted therapy to block CD47 was effective against wild-type and EGFR-mutant lung cancer cells." (PMID 34680249, 2021). "Additionally, immunohistochemistry staining results validated from the Human Protein Atlas database revealed the CD47, CD73, SIRPA, and TIM-3 protein to be upregulated in lung cancer tissues compared to normal lung tissues." (PMID 34135424, 2021). "Preclinical studies targeting the anti-phagocytic CD47 molecule showed promising results in different cancer types including lung cancer, but no data are available on its role in patients acquiring resistance to EGFR TKI treatment." (PMID 32082304, 2019). "Anti-CD47 antibody did not induce increased ADCC of lung cancer cell line cells or primary patients tumor cells compared to IgG1 isotype control." (PMID 28484448, 2017). "Anti-human CD47 antibody did not increase the apoptosis of lung cancer cells or CSCs compared to IgG isotype or anti-HLA antibodies." (PMID 28484448, 2017). "By utilizing human NK cells (CD3−CD56+CD7+) as effectors, anti-CD47 antibody did not induce increased ADCC of lung cancer cell line cells or primary patients tumor cells compared to IgG1 isotype control." (PMID 28484448, 2017). "We analyzed lung cancer and matched adjacent normal (non-tumor) tissue and revealed that CD47 is overexpressed on lung cancer cells, especially on lung CSCs." (PMID 28484448, 2017). "CD47 expression levels are also higher in LUAD patients with no smoking history compared to smokers, consistent with the higher frequency of EGFR mutations in never-smoker lung cancer." (PMID 37958404, 2023). "Our findings indicate that the combination of CEACAM1, TNFSF4, GEM, CD47, VTCN1, and TANlncSig in squamous cell carcinoma can effectively stratify patients by prognosis, highlighting these immune checkpoint receptors as potential therapeutic targets against advanced lung cancer." (PMID 36386809, 2022). "Unfortunately, endurance exercise did not change the expression levels of CD47 and CD24, and HIIT significantly increased the expression of CD47 and CD24 in lung cancer tissues, suggesting that HIIT may enhance the inhibitory effect of tumor cells on the phagocytosis of TAMs." (PMID 36186906, 2022). "In addition, HIIT significantly up-regulates the expression levels of CD47 and CD24 in lung cancer tissue, similar to PD-L1, which may also be relevant to the inhibition of macrophage phagocytic activity and the enhancement of tumor immunogenicity." (PMID 36186906, 2022). "Unlike in lung cancer, CD47 can be considered as a targeted therapeutic agent in HNSCC patients." (PMID 34680249, 2021). "However, the expression and functional significance of CD47 in Non‐Small Cell Lung Cancer (NSCLC) has not been completely understood." (PMID 32043750, 2020). "In contrast, NCPA delivered about 50% of CD47/PD‐L1 antibodies to the tumor site, indicating an about 2.5‐fold increase in tumor accumulation, which may be ascribed to the mannose‐modified NCPA capable of targeting CD206, which was overexpressed in the lung carcinoma tissue." (PMID 37132609, 2023).
lung cancer (continued). "Biomimetic SPIONs inherit native membrane proteins such as integrin αvβ3, CD47, and EGFR, enabling ligand-free homotypic recognition that has been shown to double tumor accumulation compared with non-coated SPIONs in lung cancer models." (PMID 41155938, 2025). "Although not examined in lung cancer cells, increasing SLFN11 expression in CD47 knockout Jurkat cells restored their radiosensitivity." (PMID 34571887, 2021). "Interestingly, patients with high-grade LNET and CD47 positive expression showed better PFS; to the best of our knowledge, this observation has never been reported in lung cancer." (PMID 34195295, 2021).
colorectal cancer (60 papers, 2016 to 2026). A primary or metastatic malignant neoplasm that affects the colon or rectum. "For example, CD47 protein expression has been associated with regional and distant metastases in colorectal carcinoma." (PMID 39594611, 2024). "Notably, CD47 SNP rs3804639 has been reported to be associated with the frequency of distant metastases in colorectal cancer." (PMID 37545625, 2023). "Likewise, the CD47 rs9879947 SNP has been associated with distant metastasis in a dominant model in the colorectal cancer prognosis." (PMID 34575042, 2021). "In addition, our findings demonstrate that knockout of TRIM28 in Caco2 colorectal cancer cells is associated with a pronounced upregulation of immune checkpoint molecules CD47 and CD24 on both mRNA and protein levels, particularly in clones exhibiting concurrent downregulation of CD133." (PMID 41303350, 2025). "One prior study evaluated the anti-CD47 humanized IgG4 antibody magrolimab with cetuximab in previously treated colorectal cancer, and the ORR of 2.6% was similar to our trial." (PMID 41171165, 2025). "A study involving the tumor cell line HCT116 (human colorectal cancer) has shown that CD47 regulation is influenced by IFN-γ through the action of STAT1-mediated IRF-1, leading to an upregulation of CD47 expression in tumor cells." (PMID 40909948, 2025). "Similar results were obtained in an antibody-dependent cell phagocytosis (ADCP) assay using fluorescently labeled MC38 murine colorectal cancer cells which were pre-incubated with an anti-CD47 antibody to induce phagocytosis." (PMID 39859206, 2025). "This review explores what is currently known about CD47 expression in colorectal cancer, how it interacts with the immune environment, and how it relates to patient prognosis and molecular subtypes." (PMID 41514569, 2025). "The signal regulatory protein α (SIRPα)/CD47 axis is an inhibitory phagocytosis immune checkpoint expressed on phagocytes and colorectal cancer cells, respectively, blocking phagocytosis of tumor cells." (PMID 41171165, 2025). "Preclinical studies using experimental models have provided important evidence supporting the therapeutic potential of CD47 targeting in colorectal cancer." (PMID 41514569, 2025). "Further investigation is necessary to determine the optimal use of CD47-targeted therapies in MSS colorectal cancer." (PMID 41171165, 2025). "The role of SIRPα/CD47 blockade in the treatment of MSS colorectal cancer needs to be further elucidated in future trials." (PMID 41171165, 2025). "In particular, a study on colorectal cancer radiotherapy found that after treatment, cancer cells simultaneously upregulate CD47 and PD-L1 via the ATR-mediated DNA repair signaling pathway." (PMID 40909948, 2025). "In conclusion, our findings indicate that CD47 and PD-L1 are overexpressed across various tumor tissues, particularly in colorectal cancer." (PMID 38462636, 2024). "As a result, MPB-3BP@CM NPs inherit the characteristics of the original cell membrane, exhibiting an extended circulation time in the bloodstream and effectively targeting CD47 on the cytomembrane of colorectal cancer (CRC) cells." (PMID 38862461, 2024). "CD47 has been shown to promote proliferation of colorectal cancer and adamantinomatous craniopharyngioma cells." (PMID 39039207, 2024). "In accordance, CD47 overexpression in colorectal cancer cells reduces oxygen consumption rate, which indicates a drop in the rate of mitochondrial respiration." (PMID 39039207, 2024). "It was proposed to engineer CD47-overexpressing CT26 colorectal carcinoma cells to produce CD47-enriched EV membranes capable of targeting carcinoma tumors and ensuring safe circulation in blood." (PMID 38607173, 2024). "Next, they verified the findings by analyzing NEDD8 expression in tumor-infiltrating macrophages derived from colorectal cancer (CRC) mouse models treated with CD47 blockade or a control agent." (PMID 36787255, 2023).
colorectal cancer (continued). "Although there are no data regarding the predictive and prognostic role of CD47 in rectal cancer patients treated with CRT, two large studies in colorectal cancer confirm an ominous role of CD47." (PMID 37232754, 2023). "In conclusion, this study demonstrated a novel anti-tumor mechanism of liposomal berberine and provided insights into CD47-targeted immunotherapy in colorectal cancer." (PMID 38275991, 2023). "The study evaluated CD47 SNP rs3804639 in 613 patients with colorectal cancer, and patients with the G/G genotype of the CD47 SNP rs3804639 had a lower frequency of distant metastases than those with the G/T or T/T genotypes of the CD47 SNP rs3804639." (PMID 37545625, 2023). "Overexpression of CD47 is correlated with poor prognosis in a plethora of malignancies, such as acute myeloid leukemia, colorectal cancer, and lymphoma, among others." (PMID 36939440, 2023). "Similar to what is seen in modulating PD-1 in colorectal cancer, inhibiting the CD47 checkpoint pathway has been shown to restore function of macrophages and thus led to growth inhibition and regression of tumor cells in experimental models." (PMID 35418973, 2022). "Overall, immune checkpoint inhibition represents an innovative therapeutic approach for colorectal cancer, as antibodies inhibiting PD-1 and CD47 will restore patients’ immune competence and regain the ability to eliminate cancer cells." (PMID 35418973, 2022). "Accordingly, we evaluated the effect of diHEP-DPA on TAM expression of SIRP-α, colorectal cancer cell expression of CD47, and phagocytosis." (PMID 34573091, 2021). "A publicly available proteomics dataset indicated an increased CD47 expression in SARS-CoV-2-infected Caco2 colorectal carcinoma cells." (PMID 34698067, 2021). "In contrast, cancer cell lines that have less SE signal around the CD47 locus (for example, some examples of lung, neuroblastoma and colorectal cancers) express lower levels of CD47." (PMID 28378740, 2017). "In colorectal cancer, the upregulation of the CD47 gene, as a potential immune-escape mechanism, is related to distant metastasis." (PMID 27411490, 2016). "In addition to its immunoregulatory role, CD47 has been reported to exert tumor-intrinsic, immune-independent functions in colorectal cancer." (PMID 41514569, 2025). "Although it remains uncertain whether this involves activation of the IFN-γ/STAT1 pathway, it suggests that combining CD47 and PD-L1 antibodies after colorectal cancer radiotherapy could enhance therapeutic effects and improve patient survival." (PMID 40909948, 2025). "In addition, as a dual inhibitor of SIRP-α and CD47, RRx-001 has shown excellent efficacy in the studies of solid tumors such as brain metastases, small cell carcinoma, and colorectal cancer." (PMID 38787372, 2024). "Tumor intrinsic CD47 regulates glycolysis in colorectal cancer cells by stabilizing ENO1." (PMID 38390324, 2024). "Additionally, researchers have used nanoscale metal–organic frameworks (nMOFs) to co-deliver TLR7 and CD47 antibodies to the tumor site and cooperated with PD-L1 immune checkpoint inhibitors to treat colorectal cancer." (PMID 38787372, 2024). "Taken together, our results suggested that CD47 and PD-L1 were highly expressed in tumor tissues and might play important roles in the progression of colorectal cancer." (PMID 38462636, 2024). "Baseline CD47 expression was robust in the four colorectal cancer cell lines tested." (PMID 38319147, 2024). "Furthermore, analysis of RNA-seq data from the GEO database showed that CD47 and PD-L1 expression were significantly higher in colorectal cancer patients than in the general population." (PMID 38462636, 2024). "In experimental studies in colorectal cancer, CD47 is up-regulated after irradiation in surviving cancer cells, and this has been confirmed in clinical studies, where CD47 is significantly increased in surgical specimens from patients with rectal cancer treated with short-course RT." (PMID 37232754, 2023).
colorectal cancer (continued). "They speculated that targeting the CD47-SIRPA checkpoint might be a potential therapeutic strategy to enhance antitumor immunity in colorectal cancer." (PMID 37465677, 2023). "Moreover, diHEP-DPA blocked immunosuppression by reducing the expression of SIRPα in TAMs and CD47 in colorectal cancer cells." (PMID 34573091, 2021). "We seek to explore the immune-independent functions of CD47 in colorectal cancer (CRC)." (PMID 32226539, 2020). "Besides PD-1, the CD47-SIRPα-axis seems to be a promising target in colorectal cancer." (PMID 35418973, 2022). "In order to evaluate the generalizability of PSFL‐NK13‐mediated modulation of the CD47/αvβ3 axis, we examined its efficacy in HCT‐116 colorectal carcinoma and A549 non‐small‐cell lung cancer cell lines." (PMID 41168993, 2026). "Taken together, we conclude that our anti-SIRPα mAbs effectively block the SIRPα-CD47 interaction, thereby enhancing the phagocytic activity induced by the anti-EGFR mAb on colorectal cancer cells." (PMID 40136470, 2025). "Our SIRPα mAbs competed with CD47 for binding to human SIRPα and exhibited a potent phagocytic effect when combined with the anti-EGFR antibody on colorectal cancer cell lines." (PMID 40136470, 2025). "Future research should investigate the relationship between CD47 and PD-L1 expression and the activation of the IFN-γ/STAT1 pathway in colorectal cancer radiotherapy." (PMID 40909948, 2025). "By bringing together findings from different studies, we aim to clarify the potential of CD47 as a biomarker and therapeutic target, providing insights that may support the development of more effective and personalized immunotherapy approaches for colorectal cancer." (PMID 41514569, 2025). "However, it should be noted that it has been reported that blocking the CD47/SIRPα axis may be ineffective in hypoxic colorectal cancer, as the expression of CD47 showed a negative association with hypoxia." (PMID 40385641, 2025). "Dong found that hyperoside degrades c-Myc (a flavonoid), down-regulating the expression of immune checkpoints PD-L1 and CD47, in addition to reshaping the MC38 colorectal cancer immune microenvironment in vivo to induce anti-colorectal cancer effects." (PMID 38792234, 2024). "The combination of PD-1 and CD47 blockade with 10 Gy irradiation resulted in complete remission of abscopal tumours in KP1 SCLC and MC38 colorectal cancer." (PMID 38833685, 2024). "Meanwhile, CD47 overexpression increases the levels of glucose-6-phosphate, phosphoenolpyruvate (PEP), pyruvate, and lactate in colorectal cancer cells." (PMID 39039207, 2024). "Many cancers, including colorectal cancer (CRC), exploit the expression of CD47 to escape phagocytic clearance and activate the innate immune system." (PMID 36787255, 2023). "In this preclinical human immune system patient-derived xenograft (HIS-PDX) model and phase II clinical trial, we assessed evorpacept (anti-CD47 engineered fusion protein with inactive Fc), cetuximab, and pembrolizumab (triple therapy) in microsatellite-stable (MSS) colorectal cancer." (PMID 41171165, 2025). "Inhibiting CD47 not only amplifies the local antitumour effects of a 10 Gy single-fraction radiotherapy but also triggers abscopal effects in KP1 small cell lung cancer and MC38 colorectal cancer models." (PMID 38833685, 2024). "The analysis identified that the prioritized tumor types, that is, colorectal cancer, SCCHN, and DLBCL, had tumors with higher levels of CD47-SIRPα and macrophage infiltration, and thus may be suitable targets for BMS-986351 treatment." (PMID 38319147, 2024). "Similarly, CD47 and the mannose receptor (CD206), overexpressed on the surface of colorectal carcinoma cells, were used as targets for the efficient targeting of colon cancer therapy." (PMID 38543324, 2024). "Despite evidence of similar effects for PD-1 and CD47 causing pro-tumor macrophage polarization, data regarding VISTA on colorectal cancer is not yet available." (PMID 35418973, 2022).
colorectal cancer (continued). "We hypothesize that combining CD47 blockade with therapies that further reduce myeloid immunosuppression, a key mediator of immunotherapy resistance in MSS colorectal cancer, such as KRAS inhibitor, STING agonist, TLR9 agonist, GM-CSF, or inflammasome modulation, could be effective." (PMID 41171165, 2025). "Interestingly, in colorectal cancers (CRCs), CD163-positive M2-like macrophages exhibit anti-tumor activity in tumors with low levels of the anti-phagocytotic marker CD47 and positively correlate with the expression of CD68, which predicts increases in long-term survival." (PMID 38255296, 2024). "Therefore, we identified a human colorectal cancer cell line DLD‐1 for which phagocytosis was more dependent on inhibition of the CD47‐SIRPα axis and for which phagocytosis was significantly induced in response to CD47‐SIRPα blockade alone." (PMID 37206279, 2023). "Here, using several murine tumor models, including colorectal cancer and B cell lymphoma, we revealed that tumor responsiveness to IFN-Is, but not IFN-II, is critical for the efficacy of CD47-SIRPα ICB." (PMID 38982116, 2024).